ADAMTS5 (ADAM metallopeptidase with thrombospondin type 1 motif 5)
Diseases named in the same sentence as ADAMTS5 in open-access papers (continued):
Sharing a sentence is not in itself a finding about the gene and the disease.
osteoarthritis (continued). "It has been reported that ADAMTS5 regulates osteoarthritis injury through Wnt/β-catenin signaling." (PMID 40937200, 2025). "Pharmacological inhibition of the extracellular zinc metalloprotease A Disintegrin-like And Metalloprotease domain with Thrombospondin type I motifs 5 (ADAMTS5) has been proposed as a treatment for osteoarthritis (OA), a degenerative disease characterized by cartilage loss." (PMID 41381706, 2025). "Consequently, dysregulated ADAMTS5 activity compromises the structural integrity of the extracellular matrix, contributing to several pathologies such as osteoarthritis (OA) and cancer." (PMID 41381706, 2025). "Since small molecule inhibitors of ADAMTS5 are in phase III clinical trials for osteoarthritis treatment, our data suggest that these could be repurposed to prevent OC progression." (PMID 40164572, 2025). "LncRNA MIR22HG facilitated osteoarthritis progression via targeting miR-9-3p/ADAMTS5 axis." (PMID 37779916, 2023). "The aqueous extract from Codium fragile decreased nitrite production, protein expression of iNOS, matrix metalloproteinase-13, a disintegrin and metalloproteinase with thrombospondin motifs (ADAMTS)-4, and ADAMTS-5 against IL-1β-induced osteoarthritis with the regulation of the MAPK/NF-κB signal." (PMID 37760047, 2023). "Previous studies revealed that the most active aggrecanases in human joint illness are ADAMTS-4 and ADAMTS-5 (aggrecanase-1 and aggrecanase-2, respectively), after analyzing synovial fluid samples from a variety of human joint diseases, including osteoarthritis." (PMID 37259405, 2023). "The inhibitor of HDAC could reduce the expression of ADAMTS-5 and provide a potential solution for osteoarthritis." (PMID 35599845, 2022). "In chondrocytes, cyclic stretch also stimulates the expression of ADAMTS-5 which could induce osteoarthritis." (PMID 35599845, 2022). "After eight weeks, a combination of an ADAMTS-5 inhibitor (114810) and hyaluronic acid hydrogel reduced cartilage degeneration and allowed cartilage regeneration, implying that ADAMTS-5 may be a target for osteoarthritis treatment." (PMID 34868573, 2021). "The role of ADAMTS5 in aging-related diseases such as osteoarthritis is well known." (PMID 33573338, 2021). "Many recent studies have examined the relationship between a polymorphism in the ADAMTS5 gene (rs226794) and the risk for developing osteoarthritis without definitive results." (PMID 34946864, 2021). "MMPs and ADAMTS5 contributed to cartilage destruction during osteoarthritis." (PMID 30931327, 2019). "Aggrecanase-2 (ADAMTS5) gene is responsible for aggrecan degradation that may contribute to cartilage destruction in a mouse osteoarthritis (OA) model." (PMID 30652828, 2019). "Administration of ADAMTS5 inhibitors for osteoarthritis may therefore be contraindicated in elderly patients, as they are more susceptible to influenza infection." (PMID 27855162, 2016). "In osteoarthritis cartilage, ADAMTS-5 is thought to have a more influential role than ADAMTS-4." (PMID 22394620, 2012). "However, the dual deletion of ADAMTS4 and ADAMTS5 provided significant protection against proteoglycan degradation ex vivo and decreased the severity of murine osteoarthritis in vivo." (PMID 19889209, 2009). "Although studies using transgenic mice suggest that in these murine models of degenerative joint disease, ADAMTS5 is the pathologically induced aggrecanase, our data suggest that ADAMTS4 is the aggrecanase induced by proinflammatory cytokines in the human OA synovium." (PMID 17177994, 2006). "Indeed, IL‐1β and IL‐6 were shown to induce ADAMTS5 expression in osteoarthritis." (PMID 40164572, 2025). "The dysregulation of proteinase activity is a hallmarkof osteoarthritis(OA), a disease characterized by progressive degradation of articularcartilage by catabolic proteinases such as a disintegrin and metalloproteinasewith thrombospondin type I motifs-5 (ADAMTS-5)." (PMID 36891740, 2023).
osteoarthritis (continued). "SDC4 (Syndecan-4), a target of miR-140-3p.2 but not miR-140-3p.1, has been implicated in osteoarthritis progression through activation of ADAMTS5, suggesting SDC4 suppression by miR-140-3p.2 may maintain a healthy cartilage phenotype." (PMID 32660984, 2020). "Understanding how ADAMTS5 expression is regulated and identifying a region suitable for screening libraries of compounds for a small molecule that can inhibit transcription of ADAMTS5 could prove very useful in the pursuit of osteoarthritis therapies." (PMID 18478108, 2008). "Such therapies are already being developed for the treatment of osteoarthritis, with inhibitors of ADAMTS4 and ADAMTS5 currently in phase III clinical trials." (PMID 41465277, 2025). "In a mouse model of posttraumatic osteoarthritis, curcumin has been found to slow the progression of osteoarthritis and relieve its symptoms by reducing the levels of MMP-1, MMP-3, MMP-13, ADAMTS5, IL-1β, and TNF-α." (PMID 37938371, 2024). "In knee osteoarthritis, administration of exogenous miR-17 downregulated the expression of pathological catabolic factors such as MMP13, ADAMTS5, and NOS2, thereby reducing extracellular matrix damage and alleviating the severity of osteoarthritis." (PMID 37016437, 2023). "As extracellular matrix proteins play a key role in the pathogenesis of osteoarthritis, it is indicated that ICS-CSSH promoted the synthesis and secretion of collagen II and inhibited the expression of MMP13, ADAMTS5." (PMID 36805735, 2023). "High concentrations of Mg2+ promote the synthesis of TIPM3 to further suppresses osteoarthritis by inhibiting the expression of ADAMTS4, ADAMTS5, and MMP-13." (PMID 36546928, 2022). "In the pathogenesis of osteoarthritis, the matrix-degrading enzymes MMP-13 and ADAMTS-5 play a role." (PMID 34868573, 2021). "The latest research has shown that the SOX4 can participate in the pathological changes of osteoarthritis cartilage by regulating ADAMTS4 and ADAMTS5." (PMID 34006298, 2021). "In conclusion, electroacupuncture for osteoarthritis is accomplished by upregulating the expression of HIF-1α, Sox9, and ACAN and downregulating the expression of MMP13 and ADAMTS5." (PMID 34760015, 2021). "Osteoarthritis research society international (OARSI) score in cartilage was markedly increased, along with increased MMP‐3, MMP‐13, ADAMTS‐5, ICAM‐1, ERK and p‐ERK expression." (PMID 33939302, 2021). "ADAMTS5, NOTCH1, SMAD9, and SOX9 genes, enriched in the osteoarthritis pathway, were predicted as targets of a novel miRNA (3_17250)." (PMID 32316683, 2020). "Pretreatment of human osteoarthritis chondrocytes for 2 h with IF (1, 10, and 50 μM) in medium culture reduced the expression of ADAMTS-4 and ADAMTS-5, induced by IL-1β." (PMID 32349420, 2020). "In vitro and in vivo studies demonstrated that CJM reduced the IL‐1β‐, IL‐6, IL‐17‐ and TNF‐α‐induced up‐regulation of MMP3, MMP13, ADAMTS4, ADAMTS5 and COX‐2 and blocked osteoarthritis development in a destabilization of the medial meniscus mouse model." (PMID 31148341, 2019). "In osteoarthritis, chondrocytes adopt an abnormal hypertrophic morphology and upregulate the expression of the extracellular matrix-degrading enzymes, MMP-13 and ADAMTS-5." (PMID 26705100, 2015). "Finally, we review the current literature regarding the development of synthetic inhibitors directed toward the aggrecanases ADAMTS4 and ADAMTS5, a strategy that might directly inhibit cartilage destruction and restore joint function in both rheumatoid arthritis and osteoarthritis." (PMID 25606593, 2014). "Several of these target genes such as ADAMTS5, GDF5 and LEP have been previously correlated with osteoarthritis." (PMID 19011694, 2008). "Osteoarthritis (OA) involves cartilage degradation by ADAMTS-5, but how ADAMTS-5 expression is activated remains unclear." (PMID 42211122, 2026).
osteoarthritis (continued). "The genes enriched in the osteoarthritis pathway revealed by IPA of the DEGs in the palovarotene-treated chondrocytes included various matrix catabolic genes (Adamts4, Adamts5, Mmp9, Mmp10, Mmp12, and Mmp13) and cell death-related genes (Casp1, Casp3, and Casp6)." (PMID 39062860, 2024). "Although monoclonal antibodies and small molecules have been developed to inhibit the deleterious effect of ADAMTS-5 in osteoarthritis, side effects and lack of specificity have prevented their progression towards clinical trials." (PMID 37651409, 2023). "There are currently no approved drugs (DMOADs) for the treatment of osteoarthritis, and ADAMTS-5 is a promising target for identifying DMOADs." (PMID 36803799, 2023). "Because cartilage erosion is a common pathological alteration in OA, targeting some key metalloproteinases such as MMP-3, ADAMTS-5 besides their inhibitor TIMP-3 by natural products, could be an effective strategy to protect against osteoarthritis." (PMID 37259405, 2023). "Studies have shown that Mg2+ may affect osteoarthritis by inhibiting the expression of IL-1β, TNF-α, MMP13, and ADAMTS5 genes in macrophages, synoviocytes, and chondrocytes." (PMID 36546928, 2022). "In support of this notion, in 6-month old Wnt9a∆Prx/− specimens ADAMTS5- and MMP13-positive cells were observed in the synovium, and 9-month and older Wnt9a∆Prx/− mice develop osteoarthritis-like changes in their joints (C.H. and S.T. manuscript in preparation)." (PMID 33990546, 2021). "For example, WISP-3 overexpression in normal cartilage (C-28/I2) cells dramatically reduces the expression of ADAMTS-4 and ADAMTS-5, and markedly elevates matrix metalloproteinase-1 (MMP-1) and MMP-10 expression, leading to the degradation of cartilage and the development of osteoarthritis." (PMID 34680447, 2021). "The changes in expression of the DEGs listed in the osteoarthritis pathway included strong down-regulation of cartilage matrix molecules (COL2A1, MATN3, and ACAN) and up-regulation of matrix proteases (ADAMTS5 and MMP13) and apoptosis-related molecules (CASP4)." (PMID 32294904, 2020). "The ECM enzyme ADAMTS5, a member of the ADAMTS (A Disintegrin-like and Metalloproteinase with Thrombospondin-1 motifs) protein family, cleaves large proteoglycans such as aggrecan, leading to the destruction of cartilage and osteoarthritis." (PMID 27855162, 2016). "For the 8 gene loci ESR1 rs2234693, CYP19A1 rs700518, ADAM12 rs3740199, ACE I/D rs4340, VDRrs731236, TGF-β rs1982073, FAS rs1800682, ADAMTS5 rs226794, the cumulative sample sizes were deemed sufficient to conclude that they are not correlated with osteoarthritis." (PMID 39248710, 2024). "As one of the most important protein-degrading enzymes, ADAMTS-5 plays an important role in the regulation of cartilage homeostasis, while miRNA-140 is specifically expressed in cartilage, which can inhibit the expression of ADAMTS-5 and delay the progression of OA (osteoarthritis)." (PMID 36803799, 2023). "ADAMTS5 has a direct connection with Osteoarthritis pathway while LAMA4 is not." (PMID 34970658, 2019). "In our study, catabolic genes, including MMP-3 and -9 and ADAMTS5, and the proinflammatory cytokines, including CCL-2 and-5 and CXCL1, were also inhibited by DHA treatment, suggesting the potential role of DHA in maintaining cellular homeostasis and treating osteoarthritis." (PMID 27941926, 2016).
Arthritis (30 papers, 2006 to 2024). Inflammation of a joint. "ADAMTS5 has been implicated in classic morphogenesis during development as well as in chronic diseases such as arthritis and atherosclerosis." (PMID 29518972, 2018). "In mice, the aggrecanase ADAMTS5 is a potent mediator of cartilage destruction, as ADAMTS5 deficiency results in significant protection against cartilage erosion during experimental arthritis." (PMID 21799806, 2011). "The secreted metalloprotease ADAMTS4 and ADAMTS5 are responsible for the degradation of cartilage proteoglycan in arthritis." (PMID 39275306, 2024). "According to our findings, rats with MIA-induced arthritis had marked elevation in serum levels of ADAMTS-5 and MMP-3 than did normal rats." (PMID 37259405, 2023). "It has been verified that ADAMTS5 is a major cartilage degrading enzyme in arthritis and is positively related to articular cartilage degradation." (PMID 36092909, 2022). "It remains to be established if inhibitory RNA-based ADAMTS5 inactivation can modulate arthritis progression in vivo." (PMID 34268335, 2021). "We will also provide an overview of past and current efforts to develop ADAMTS isotype-specific inhibitors that mainly target the aggrecanases ADAMTS4 and ADAMTS5 and are currently being pursued as potential disease-modifying arthritis drugs." (PMID 34268335, 2021). "miR-30a expression was downregulated in arthritis patients and was negatively correlated with ADAMTS5 expression." (PMID 29757957, 2018). "In animal model of arthritis, ADAMTS-5 alone is the critical enzyme to contribute for joint destruction were also reported." (PMID 29137610, 2017). "Several experiments have demonstrated that neutralizing antibodies and other methods play a significant role in the models of arthritis in restraining ADAMTS-4 or ADAMTS-5." (PMID 28167976, 2017). "Among the 19 members of ADAMTS family, ADAMTS-4 and ADAMTS-5 have received significant attention in the pathology of arthritic joint diseases because they are the most efficient aggrecanases in vitro." (PMID 28167976, 2017). "ADAMTS5 has become a major drug target for arthritis therapy as ADAMTS5 knockout mice (Adamts5-/- mice) are resistant to aggrecan cleavage in articular cartilage and are thus protected from experimentally induced arthritis." (PMID 27855162, 2016). "Aside from the documented role in arthritis, ADAMTS5 has been shown to play a role in embryonic development, including limb and cardiac morphogenesis, and skeletal muscle development through its versican remodelling properties." (PMID 27855162, 2016). "ADAMTS-5 was found to be the dominant aggrecanase in mouse models of arthritis, and a recent report indicates that ADAMTS-8, -15, -16, and -18 are expressed at very low levels in mouse cartilage." (PMID 19919704, 2009). "β2-AR mediated downregulation of MMPs and ADAMTS5 genes in chondrocytes could be a positive sign for matrix protection in arthritis." (PMID 36188601, 2022). "Furthermore, the transgenic mice with overexpression of miR-140 were reported to be resistant to antigen-induced arthritis via the regulation of ADAMTS5, a major cartilage matrix-degrading protease in OA." (PMID 33670901, 2021). "The development of inhibitors for ADAMTS proteases is primarily focused on inhibiting ADAMTS4 and ADAMTS5 due to their prominent role in cartilage destruction in arthritis where both proteases degrade aggrecan, a major structural proteoglycan in the articular cartilage." (PMID 34268335, 2021). "In combination with adeno-associated virus (AAV)-mediated gene delivery, one could envision that ADAMTS5 activity could be significantly reduced in knee joints affected by arthritis and halt disease progression." (PMID 34268335, 2021). "ADAMTS-4 and ADAMTS-5 were identified as the major cartilage aggrecanases in arthritis." (PMID 35140604, 2021).
Arthritis (continued). "Furthermore, a function study reported that the S100A8 stimulation in chondrocytes induces upregulation of mRNA levels of MMP-2, MMP-3, MMP-9, and MMP-13 and ADAMTS-4 and ADAMTS-5 in experimental murine arthritis, which is similar to our findings." (PMID 31815654, 2019). "Both ADAMTS4 and ADAMTS5 are responsible for aggrecan degradation in a human model of arthritis." (PMID 29757957, 2018). "In mice, however, ADAMTS5 alone is the critical enzyme, as Adamts5−/− mice show significantly reduced joint destruction when compared to wild-type or Adamts4−/− mice in surgical and allergen-induced models of arthritis." (PMID 26025392, 2015). "However, evidence of their cooperative roles in cartilage degradation and common activation by inflammatory cytokines suggests that both ADAMTS4 and ADAMTS5 represent important therapeutic targets in arthritis." (PMID 25606593, 2014). "The plethora of emerging small-molecule ADAMTS aggrecanase inhibitors gives hope that some will be efficacious and tolerable and that those that are specific to ADAMTS5 could be developed as novel therapeutics for arthritis patients in the near future." (PMID 25606593, 2014). "The basal (day 0) relative expression levels of the ADAMTSs further suggest that ADAMTS-4 and -9 may be important for cartilage homeostasis and support the hypothesis that in the bovine system, as in murine arthritis, ADAMTS-5 may be critically important." (PMID 16919164, 2006). "However, simultaneous inhibition of ADAMTS4 and ADAMTS5 may be desired in modifying arthritis progression." (PMID 34268335, 2021). "Therefore, an ideal small molecule or biologic inhibitor for ADAMTS5 as a disease modifying arthritis drug would be, one, highly specific for ADAMTS5; two, spare substrates other than aggrecan; and, three, deliverable to or become selectively activated in articular cartilage or the synovium." (PMID 34268335, 2021). "It is interesting to speculate that while ADAMTS5 is clearly the predominant aggrecanase responsible for acute aggrecanolysis in mouse cartilage in vitro and in different in vivo arthritis models, perhaps synovial ADAMTS4 plays a role in later stages of disease." (PMID 32059749, 2020). "Furthermore, ADAMTS5 is considered one of the most important aggrecan-degrading enzymes in arthritis and may also promote lipoprotein binding in atherosclerosis." (PMID 29518972, 2018). "However, whether ADAMTS4 or ADAMTS5 is predominately responsible for the cleavage of aggrecan in arthritis in humans remains controversial." (PMID 25606593, 2014). "Knocking out WTAP in chondrocytes decreased the m6A level and significantly decreased the mRNA (ADAMTS4, ADAMTS5, MMP13, IL-6, IL-8, iNOS) and protein levels of arthritis-related genes (ADAMTS4, ADAMTS5, MMP13) in the OA cell model." (PMID 38172596, 2024). "In the ERN1 cKO ACLT mouse model, more severe loss of proteoglycan in safranin O staining, a significantly higher arthritis score, elevated expression of MMP13 and ADAMTS5, and reduced expression of aggrecan and Col2 were observed." (PMID 37907740, 2023). "Several clinical trials have been conducted to test the safety and efficacy of arthritis-modifying candidate drugs that reduced aggrecanase activity, i.e., inhibited ADAMTS4 and ADAMTS5 in preclinical studies." (PMID 34268335, 2021). "An ADAMTS5 antibody against an epitope in the ancillary domain (CRB0017, Rottapharm) also ameliorated arthritis disease progression in knee joints of mice." (PMID 34268335, 2021). "Among ADAMTS proteases involved in arthritis, α2M was shown to inhibit both ADAMTS4 and ADAMTS5 in a dose-dependent manner." (PMID 34268335, 2021). "Due to their prominence in arthritis, the regulation of ADAMTS4 and ADAMTS5 gene expression by pro-inflammatory cytokines has been studied to some extent." (PMID 34268335, 2021).